UBE2O (ubiquitin conjugating enzyme E2 O)
Diseases named in the same sentence as UBE2O in open-access papers (continued):
Sharing a sentence is not in itself a finding about the gene and the disease.
memory impairment (1 paper, 2020). "Specifically, CKD‐504 increased acetylation of several chaperones and E3 ligases as well as tau itself, resulting in recruitment of the novel tau targeting E3 ligases such as UBE2O and RNF14 to tau, which lead to the rescue of synaptic pathology and memory impairment in ADLPAPT mice." (PMID 31763743, 2020).
osteosarcoma (1 paper, 2025). A usually aggressive malignant bone-forming mesenchymal neoplasm, predominantly affecting adolescents and young adults. "Employing in vitro and in vivo models, the authors established that UBE2O overexpression robustly enhances osteosarcoma cell proliferation and tumorigenesis, whereas UBE2O knockdown significantly attenuates these oncogenic processes." (PMID 40426910, 2025). "ATO also exhibits inhibitory effects on osteosarcoma by cross-linking adjacent cysteines within the catalytic domain of UBE2O, thereby inhibiting its E3 ubiquitin ligase activity." (PMID 40426910, 2025). "In summary, UBE2O promotes osteosarcoma progression by degrading L3MBTL2, disrupting its nuclear condensates, derepressing IFIT2 transcription, and activating the TNF/NF-κB pathway." (PMID 40426910, 2025). "This study elucidates UBE2O’s oncogenic role in osteosarcoma, and identifies a potential therapeutic target for innovative treatment strategies." (PMID 40426910, 2025). "UBE2O exhibits a negative correlation with L3MBTL2 in osteosarcoma, and its high expression predicts poor prognosis." (PMID 40426910, 2025).
thyroid cancer (1 paper, 2025). "Integrating these findings, the authors proposed a regulatory mechanism involving the UBE2O/PLEKHG4/RhoGTPases axis in thyroid cancer progression." (PMID 40426910, 2025). "Collectively, UBE2O modulates PLEKHG4 stability, which subsequently influences RhoGTPase activity, thereby driving thyroid cancer progression." (PMID 40426910, 2025).
viral infection (1 paper, 2018). "In this way, UBE2O likely acts to potentiate transcription by ubiquitinating HEXIM1 and promoting its sequestration in the cytoplasm, a mechanism co-opted by Tat during viral infection." (PMID 29845934, 2018).
tumor (25 papers, 2017 to 2025). "This downregulation appears to be closely linked to MM initiation and progression, suggesting a tumor-suppressive role for UBE2O in MM." (PMID 40426910, 2025). "The overexpression of UBE2O amplifies HIF1α targets, while its deficiency suppresses these targets, thereby inhibiting tumor progression." (PMID 40426910, 2025). "High UBE2O expression is associated with poor prognosis, larger tumor volume, higher Gleason score, lymph node/distant metastases (such as to the liver and lung), and aggressive molecular subtypes." (PMID 40426910, 2025). "The loss of AMPKα2 driven by UBE2O activates mTORC1, enhancing glycolysis, biosynthetic pathways, and tumor growth." (PMID 40426910, 2025). "The deregulation of UBE2O and its subsequent abnormal expression occur in many types of tumor and are associated with several human diseases." (PMID 39272922, 2024). "UBE2O deficiency can severely impair tumor initiation, growth, and metastasis while also inhibiting the metabolic reprogramming in tumor cells." (PMID 38586328, 2024). "UBE2O overexpression was prominently associated with advanced tumor stage, high tumor grade, venous infiltration, and reduced HCC patients' survivals." (PMID 34790050, 2021). "UBE2O has been reported to target several proteins for ubiquitination and implicate in chromatin-associated protein nuclear transport, adipogenesis, tumor progression, and metastasis." (PMID 32901121, 2021). "UBE2O, an E2/E3 hybrid ubiquitin-protein ligase, has been implicated in the regulation of adipogenesis, erythroid differentiation, and tumor proliferation." (PMID 32901121, 2021). "BC patients with high UBE2O expression tend to have a high risk of tumour metastasis and poor prognosis." (PMID 31907353, 2020). "In contrast, UBE2O has been associated with both tumor-promoting and tumor-inhibiting functions." (PMID 40983751, 2025). "In vivo, UBE2O-deficient xenografts exhibit reduced tumor growth under IFN-α treatment." (PMID 40426910, 2025). "Thus, UBE2O targets several proteins for ubiquitination and has been implicated in chromatin-associated protein nuclear transport, adipogenesis, tumor progression, and metastasis." (PMID 35668470, 2022). "In recent years, studies have demonstrated that UBE2O plays a significant role in carcinogenesis and tumor progression." (PMID 40426910, 2025). "The dual role of UBE2O in cancer (oncogenic vs. tumor-suppressive) is likely closely related to tumor type-specific microenvironments, substrate selectivity, and differences in signaling pathways." (PMID 40426910, 2025). "In a nude mouse xenograft model, UBE2O re-expression significantly delayed MM tumor growth and extended survival, accompanied by elevated apoptosis in c-Maf-positive MM cells." (PMID 40426910, 2025). "The study further demonstrated that restoring UBE2O expression in MM xenograft tumors markedly delayed tumor growth and prolonged survival in tumor-bearing mice." (PMID 40426910, 2025). "In this review, we summarize the contributions of UBE2O to tumor development and elucidate the mechanisms by which this signaling network regulates oncogenic processes." (PMID 40426910, 2025). "Mechanistically, UBE2O overexpression drives tumor progression and metastasis by stimulating cell proliferation, migration, and epithelial–mesenchymal transition (EMT), ultimately leading to reduced overall survival in patients." (PMID 40426910, 2025). "In vivo, UBE2O overexpression accelerates tumor growth (increased volume/weight) in subcutaneous xenograft models, whereas UBE2O silencing inhibits tumor progression." (PMID 40426910, 2025). "In terms of targeted intervention, ATO can enhance the tumor-suppressive function by inhibiting UBE2O activity, but its specificity and toxicity require optimization." (PMID 40426910, 2025). "By degrading L3MBTL2, UBE2O depletes this tumor suppressor protein, thereby compromising its tumor-suppressive function." (PMID 40426910, 2025).
tumor (continued). "These therapeutic strategies require further optimization and validation based on UBE2O’s tumor type-specific mechanisms." (PMID 40426910, 2025). "In xenograft models, combining UBE2O silencing with radiotherapy synergistically inhibited tumor growth compared to radiotherapy alone." (PMID 40426910, 2025). "In a subcutaneous xenograft mouse model, UBE2O re-expression delayed MM tumor growth, correlating with c-Maf downregulation and the activation of apoptotic pathways." (PMID 40426910, 2025). "All this evidence supports the strong connection that exists between UBE2O deregulation and tumor initiation and progression." (PMID 39272922, 2024). "The results in the in vivo animal models confirmed that the tumor volume was significantly lower in the UBE2O knockdown group than in the control group after administration of the same interferon treatment regimen (p < 0.01)." (PMID 38129382, 2023). "Previous studies reported that in other tumor types, UBE2O mediates the degradation of AMPKα2 and TRAF6, thus affecting the AMPK and NFKB pathways, respectively, as well as EMT, DNA repair, and lipid metabolism." (PMID 38129382, 2023). "UBE2O promoted the migration, invasion, and proliferation of tumor cells by activating the AMPKα2/mTOR pathway in HCC." (PMID 34790050, 2021). "In cancer cells, UBE2O positively regulates aerobic glycolysis and cellular biosynthesis; the deactivation of UBE2O can switch off the tumor cells’ glycolytic and biosynthetic programs." (PMID 34451875, 2021). "Abnormal expression of UBE2O exists in many types of human cancers, and deregulation of UBE2O plays crucial roles in tumor progression and metastasis." (PMID 34976998, 2021). "It has been documented that UBE2O targets AMPKα2 for degradation to facilitate tumor progression and metastasis." (PMID 32901121, 2021). "Then, we revealed that the increased level of UBE2O was closely correlated with advanced tumor stage, venous infiltration, high tumor grade, and poor prognosis of HCC." (PMID 34790050, 2021). "UBE2O knockdown in MDA-MB-231 cells suppressed tumour growth and lung metastasis in MDA-MB-231 xenograft mouse models." (PMID 31907353, 2020). "We found that the UBE2O state was positively correlated with tumour size (p = 0.014), axillary lymph node status (p = 0.038) and clinical stage (p = 0.019)." (PMID 31907353, 2020). "Data from Gene Expression Profiling Interactive Analysis showed that UBE2O transcription was upregulated in tumour tissues." (PMID 31907353, 2020). "As expected, UBE2O knockdown markedly suppressed xenograft tumour size and yielded better tumour-free survival." (PMID 31907353, 2020). "Knockout of Ube2o attenuated tumour development in mouse models of both breast and prostate cancer, supporting the idea that the protein has tumour-promoting functions." (PMID 31288625, 2019). "More importantly, UBE2O induces c-Maf expressing MM cell apoptosis and delays MM tumor growth in mice." (PMID 28673317, 2017). "When it is restored, UBE2O induces MM cell apoptosis and delays MM tumor growth in nude mice, suggesting UBE2O is probably a tumor suppressor protein against MM." (PMID 28673317, 2017). "Since FAs maturation mediated by UBE2O-catalyzed CTNNA1 ubiquitylation could hypothetically reduce cell migration, it is possible that the tumor-inhibiting properties of UBE2O are linked to this function." (PMID 40983751, 2025). "High UBE2O expression is correlated with poor prognosis (shorter overall/recurrence-free survival), larger tumor size, lymph node metastasis, higher histological grade, HER2 positivity, and a higher prevalence of the triple-negative breast cancer (TNBC) subtype." (PMID 40426910, 2025). "In mouse models, ATO treatment effectively inhibited tumor growth, similar to UBE2O gene knockout." (PMID 40426910, 2025). "Although further studies are needed, UBE2O regulation could be a promising strategy in the treatment of different human neoplasia." (PMID 39272922, 2024).
tumor (continued). "Studies have reported that Ube2o has carcinogenic or tumor suppressive roles in human cancers." (PMID 37378749, 2023). "Our research suggests that IFIT3 has tumor-suppressive effects, while UBE2O acts as an oncogene." (PMID 38129382, 2023). "In addition, UBE2O has been reported to accelerate tumor progression by modulating c-myc via the UBE2O/Mxi1 axis and UBE2O/AMPKα2/mTORC1 axis." (PMID 36068586, 2022). "It has been found that drugs regulating UBE2O activity function as a form of cancer therapy, as the obstructing of UBE2O with ATO has an impact on tumor biology comparable to that of UBE2O deficiency Human Tumor TMA Analysis." (PMID 34451875, 2021). "UBE2O enhanced the malignant behaviors of tumor cells by regulating the AMPKα2/mTOR pathway in HCC." (PMID 34790050, 2021). "In the first study, the UBE2O-α2 axis was postulated as a target for cancer therapies since UBE2O inhibition or Ube2o gene deletion restored α2-subunit levels, or impaired tumor initiation, growth and metastasis, and switched off tumor cell metabolic reprogramming in mice." (PMID 33513781, 2021). "Recent studies report the oncogenic or tumor-suppressive role of UBE2O in human cancers 14-19." (PMID 34790050, 2021). "Previous studies reported that UBE2O ubiquitinates AMPKα2 in skeletal muscle cells and tumor cells." (PMID 32375794, 2020). "Previous studies have demonstrated that degradation of c-Maf or interference of c-Maf leads to delayed MM tumor growth in nude mice; we wondered whether UBE2O generated similar effects on MM tumor growth in vivo." (PMID 28673317, 2017). "Therefore, UBE2O downregulated c-Maf and delayed MM tumor growth." (PMID 28673317, 2017). "Consistent with this, xenograft models revealed that UBE2O knockout suppresses EMT, angiogenesis, and tumor growth in HNSCC." (PMID 40426910, 2025). "The pro-tumorigenic effects of UBE2O are mediated through its interaction with BIN1 (Bcl-2-interacting protein 1), a tumor suppressor that antagonizes c-Myc transcriptional activity." (PMID 40426910, 2025). "Clinically, high UBE2O expression correlates with poor prognosis in HCC patients, advanced tumor stage, high histological grade, and venous infiltration." (PMID 40426910, 2025). "Functional experiments confirmed that UBE2O acted as an oncogene in HCC and facilitated the proliferation and mobility of tumor cells." (PMID 34790050, 2021). "PTRF and UBE2O (ubiquitin-conjugating enzyme E2O) are other examples of genes that were not affected in the tumor but significantly regulated in both BCPAP (xPTRF = −31.50, xUBE2O = 28.86) and 8505C (xPTRF = -58.42, xUBE2O = 11.70) cell lines." (PMID 38790250, 2024). "Exosomal circPDK1 acts as a scaffold to enhance the interaction between ubiquitin conjugating enzyme E20 (UBE2O) and bridging integrator 1 (BIN1), and it induces UBE2O-mediated degradation of BIN1, a protein that inhibits tumor progression by suppressing c-myc transcriptional activity." (PMID 37753074, 2023). "Nevertheless, if there was no AMPKα2 or Mix1 expression in cancer cells, ablation of UBE2O expression did not display dramatically anti-tumor effects." (PMID 36443833, 2022). "In addition, UBE2O can function in BMP7-induced adipogenesis via monoubiquitination of SMAD6 and also in chromatin remodeling by ubiquitinating the tumor-suppressive DUB BAP1." (PMID 37533513, 2022). "Then, we explored the effect of UBE2O on EMT, which is a crucial process in tumour metastasis." (PMID 31907353, 2020). "Furthermore, circPDK1 functions as a scaffold to enhance the interaction between 65 kDa Myc box-dependent interacting protein 1 (BIN1), a tumor suppressor that interacts with c-myc to limit its transcriptional activity, and UBE2O, thereby facilitating BIN1 degradation by UBE2O." (PMID 40004471, 2025).
tumor (continued). "Furthermore, simultaneous knockdown of IFIT3 and UBE2O did not significantly affect the subcutaneous tumor volume compared with that in the control group; however, knockdown of UBE2O alone resulted in a significant reduction in tumor volume (p < 0.001)." (PMID 38129382, 2023).
cancer (24 papers, 2019 to 2025). A tumor composed of atypical neoplastic, often pleomorphic cells that invade other tissues. "This article reviews the molecular functions of UBE2O and its underlying mechanisms in cancer, metabolic diseases, and age-related diseases." (PMID 40426910, 2025). "In terms of metabolic reprogramming, UBE2O drives metabolic reprogramming, which is a hallmark of cancer." (PMID 40426910, 2025). "In cancer, the presence of UBE2O causes upregulation in the mTOR-HIF1a pathway, which is strongly correlated with pro-growth, glycolytic, and biosynthetic programs." (PMID 34451875, 2021). "Deregulation of UBE2O has been associated with several human diseases, especially cancers." (PMID 34976998, 2021). "Another example is provided by the cancer-associated ubiquitin ligase, UBE2O." (PMID 33375416, 2020). "Ectopic UBE2O overexpression is associated with a variety of human diseases, especially cancers." (PMID 31907353, 2020). "First, the substrate specificity of UBE2O and its functional diversity in different cellular contexts need further investigation to clarify its precise role in various types of cancer." (PMID 40426910, 2025). "The Warburg effect—preferential glycolysis under oxygen-rich conditions—is suppressed in UBE2O knockout cells, further emphasizing the role of UBE2O in maintaining cancer metabolism." (PMID 40426910, 2025). "We hope this review will stimulate further research to enhance our understanding of UBE2O-mediated tumorigenesis and accelerate the discovery of novel therapeutic strategies targeting UBE2O in cancer treatment." (PMID 40426910, 2025). "As a key component of the UPS, UBE2O has demonstrated significant potential in recent research across fields such as cancer, AD, and metabolic disorders." (PMID 40426910, 2025). "ATO has demonstrated significant inhibitory effects on various cancers through its ability to suppress the activity of UBE2O." (PMID 40426910, 2025). "In summary, this review underscores UBE2O importance in cancer biology and its potential for future therapeutic applications." (PMID 39272922, 2024). "UBE2O is localized in the 17q25 chromosome region, which has been found to be amplified in different cancers, including breast, prostate, gastric, kidney, and ovarian cancers." (PMID 39272922, 2024). "Ultimately, our review aims to highlight the potential role of UBE2O as a therapeutic target and offers new perspectives for developing targeted treatments for human cancers." (PMID 39272922, 2024). "In HCC, UBE2O promotes lipid metabolic reprogramming and cancer progression by facilitating the ubiquitination of HADHA." (PMID 38129382, 2023). "UBE2O progressively promotes cancer growth and progression via upregulating AMPK/mTORC1, which induces HIF1α, completing a positive feedback loop to confer a continuous hypoxic environment favoring cancer cell progression and stemness." (PMID 37583933, 2023). "Since exosomes play an important role in malignant tumor growth and PTRF included in exosomes is a biomarker for several malignant tumors, increasing UBE2O expression in cells has the potential to be developed as a novel approach for cancer treatment." (PMID 36443833, 2022). "This underscores the importance of UBE2O’s regulation of the mTOR-HIF1a pathway for both the angiogenic signaling pathway, and the neovascularization necessary for cancer growth and metastasis." (PMID 34451875, 2021). "Overexpressed in numerous human cancers, UBE2O targets AMPK for ubiquitination and degradation, which subsequently fosters the activation of the mTOR-HIF1a pathway." (PMID 34451875, 2021). "Depletion of UBE2O with specific siRNAs led to an elevation in endogenous Mxi1 protein levels in different cancer cells under steady-state conditions and after DNA damage." (PMID 32901121, 2021). "Taken together, these results confirmed that UBE2O plays a vital role in the cancer-promoting function of HCG18 in BC cells." (PMID 34976998, 2021).